EGFR (epidermal growth factor receptor)
Diseases named in the same sentence as EGFR in open-access papers (continued):
Sharing a sentence is not in itself a finding about the gene and the disease.
tumor (continued). "Altogether, these results highlight i) the different tumor responses against the EGFR TKI erlotinib and osimerinib and against bevacizumab for A549, PC9 and H1975 tumors and ii) demonstrate the efficacy of osimertinib plus bevacizumab in some NSCLC subpopulation." (PMID 38935790, 2024). "By monitoring TMB with liquid biopsies, conclusions may be drawn about the efficacy of ICIs and patients who did not qualify initially might do so over the course of their treatment – i.e. making the tumor “hotter” by using anti-EGFR therapy." (PMID 39080202, 2024). "Tumor cell alterations conferring resistance to EGFR-TKIs may occur via proteins other than the targeted oncoprotein." (PMID 38764025, 2024). "Targeted NGS analyses of the tumor and PDC both identified a PIK3CA M1004I mutation and an EGFR 19 deletion, which together may have caused the resistance to erlotinib." (PMID 38398169, 2024). "In addition, the researchers found that FGF8 not only promotes tumor cell growth, but also upregulates EGFR expression, leading to increased angiogenesis and resistance to EGFR inhibitors." (PMID 38816668, 2024). "EGFR-targeting molecules could redirect the immune response against tumor cells by tethering effector cells, such as CD3-epsilon (CD3E) T cells, to the surface of cancer cells." (PMID 38654239, 2024). "As hypothesized, we detected significantly higher RS on ecDNA in GBM39ec tumour cells, as measured by colocalization of pRPA2-S33 and EGFR FISH signal compared to GBM39HSR tumour cells, especially in EdU-positive cells." (PMID 39506153, 2024). "Our data may provide rationale for the mechanistic investigation of the combination of ICI with EGFR inhibition in tumours with EGFR CNG as a means to enhance anticancer immune responses and improve the efficacy of immunotherapies." (PMID 38744099, 2024). "Therefore, the present study suggests that NCAPD3-knockdown-induced differentially expressed genes (DEGs) such as CRNDE, EDN1, and JUNB can regulate cell and tumor invasion through EGFR and PLAUR." (PMID 38711992, 2024). "Meanwhile, EGFR mutations were not correlated with age, drinking history, serum tumor markers, tumor long diameter, or TNM stage (P> 0.05 for all)." (PMID 39364008, 2024). "HER2 forms heterodimers with EGFR that initiate a strong tumor growth signal." (PMID 38711454, 2024). "The expression and function of the mutant EGFR gene may contribute to the varying patterns of tumor growth, leading to the distinct skewness among patients." (PMID 38811597, 2024). "Moreover, αvβ6 expression showed a better incremental relationship with tumor malignancy than did EGFR." (PMID 38633382, 2024). "The system specifically targeted cancer cells expressing EGFR, resulting in inhibited tumor growth." (PMID 38200584, 2024). "Interestingly, patients who develop mutations in the EGFR-ECD experience greater and more lasting tumor responses con anti-EGFR treatment, compare to patients who develop other mechanisms of resistance, such as RAS mutations." (PMID 38711991, 2024). "The molecular testing (Oncomine Focus Assay) of the tumour cells from the pleural effusion showed persistent EGFR p.L858R and HER2 p.S310F mutations, but no ROS1 fusion transcripts." (PMID 38891886, 2024). "Notably, majority targets of TB-2 are implicated in tumor therapy, including TGM2, KIT, EGFR, AURKA, FASN, and CDK2, which have garnered extensive research attention." (PMID 39376614, 2024). "Analysis of single-cell RNA transcriptomics suggested that the tumor cells dramatically upregulated EGFR and MET in response to PD-L1 immunotherapy, potentially creating a metabolic state fit for tumor persistence in the tumor microenvironment (TME) and rendered pembrolizumab ineffective." (PMID 38916448, 2024). "This reduction in EGFR expression could elucidate the mechanism behind the observed decrease in tumor aggressiveness and increased afatinib sensitivity, highlighting the therapeutic potential of inhibiting PSMC1 and PSMD11 in LUAD." (PMID 38557672, 2024).
tumor (continued). "As a result, high-level EGFR expression will likely be necessary to induce anti-tumor effects." (PMID 38203786, 2024). "Since VEGF has previously been reported to synergize with EGFR in promoting tumor development, we used IHC, qRT-PCR, and confocal microscopy to determine whether EGFR was overexpressed in the ORFV-infected tissues." (PMID 38613413, 2024). "High tumor B7-H3 expression was significantly associated with pT stage (p = 0.02), lymph node metastasis (p=0.027), lymphovascular invasion (LVI, p = 0.035), distant metastasis (p=0.001) and EGFR expression (p=0.019)." (PMID 38370387, 2024). "Clinical evidence, supported by single‐cell RNA sequencing and multiplex immunostaining of tumor tissues, confirms the presence of IL32‐expressing pericytes closely interacting with β5‐integrin‐expressing cancer cells in EGFR‐mutated patients, impacting therapeutic response and prognosis." (PMID 39435643, 2024). "This notion is supported by several recent studies providing experimental evidence that tamoxifen or fulvestrant treatment of HNSCC cell lines increases apoptosis, reduces invasion in combination with EGFR inhibition, and sensitizes tumor cells to fractionated irradiation." (PMID 38279245, 2024). "Eight protein tumor markers (CA125, CA15.3, CEA, CYFRA 21-1, HE4, NSE, ProGRP, and SCCA) were measured using electrochemiluminescent assays, and ctDNA mutations in EGFR, KRAS, and BRAF were determined using droplet digital PCR in the blood of 1096 patients suspected of having lung cancer." (PMID 39123371, 2024). "Interestingly, the deregulation of PNN was related to CRC tumor progression in vitro and in vivo, activating the EGFR/ERK pathway." (PMID 38892168, 2024). "Based on these observations, it is hypothesized that elevated intracellular H2O2 levels serve as a second messenger during epidermal growth factor receptor signaling, hence promoting tumour formation." (PMID 38336645, 2024). "Notably, the tumor exhibited the highest fluorescence intensity, demonstrating successful targeting by the nanocomposite through the anti-EGFR affinity moieties." (PMID 39525484, 2024). "Moreover, the therapeutic effect of MNB-Pyra Nbs in vivo was further evaluated on Hela tumor bearing model with moderate EGFR expression." (PMID 39138197, 2024). "Overexpression of EGFR or its ligands has been shown to have a significant pro-tumor effect." (PMID 38816668, 2024). "Furthermore, REGN5093-M114 demonstrated potency in reducing tumor growth in EGFR-mutant NSCLC cases with specific genetic alterations, such as PTEN loss or MET Y1230C mutation, especially after previous treatment with osimertinib and savolitinib." (PMID 39015563, 2024). "EGFR high expression (EGFRhigh) status activates more downstream signaling pathways and promotes proliferation, metastasis and invasiveness of tumor cells, resulting in poor tumor prognosis." (PMID 39624043, 2024). "Both Axl and EGFR have been identified as key players in NPC tumor cell invasiveness." (PMID 39594573, 2024). "Firstly, the availability was limited to the treatment as monotherapy for patients with a tumor proportional score (TPS) of PD-L1 ≥ 50% without the driver mutations epidermal growth factor receptor (EGFR) and anaplastic lymphoma kinase (ALK)." (PMID 38601759, 2024). "In case NCCLu-263, the Cobas® EGFR mutation test identified an EGFR 19 deletion mutation in the tumor, but the patient did not display dramatic improvement after receipt of erlotinib." (PMID 38398169, 2024). "Anti-EGFR nanobodies fused with glycosylphosphatidylinositol (GPI)-anchor signal peptide enriched on the surface of exosomes increase the binding of exosomes to EGFR positive tumor cells." (PMID 38589859, 2024). "Similarly, the tumor suppressor let-7-5p family members play an important modulatory role in multiple human cancers including HCC by repressing oncogenic targets such as EGFR/LIN28B/ HMGA2 and C-MYC that are all important players in oncogenesis." (PMID 38256049, 2024).
tumor (continued). "The results demonstrated that the combination therapies induced marked tumor growth suppression for more than 1 month, suggesting that brigatinib with any of the anti-EGFR antibodies is effective against osimertinib-resistant EGFR-del19/C797S or -del19/T790M/C797S tumors." (PMID 38396251, 2024). "The AREG/EGFR axis induces tumor cell proliferation through multiple signaling pathways." (PMID 38904011, 2024). "Given that ICIs can facilitate immune rejection and tumor regression by augmenting cytotoxic lymphocytes, the combination of anti-EGFR therapy with ICIs may yield a synergistic antitumor effect." (PMID 38242940, 2024). "When administered as a mRNA-LNP combination (ComboRNA), the growth of EGFR-positive tumors in immunocompetent mice was significantly inhibited, resulting in tumor regression in 20% of cases with no associated toxicity." (PMID 39835115, 2024). "Furthermore, epidermal growth factor receptor (EGFR) overexpression or mutations are commonly observed, contributing to unchecked tumor growth through dysregulated activation of the epidermal growth factor receptor pathway." (PMID 39735155, 2024). "Furthermore, chemical inhibition of HSP70 potentiates EGFR–tyrosine kinase inhibitor-induced tumor reduction in vivo." (PMID 39470734, 2024). "Effective tumor-specific labeling was achieved using anti-EpCAM 9C4 and anti-EGFR AY13 mAbs." (PMID 38883274, 2024). "It is suggested that EGFR may influence prognosis through its direct expression and the modulation of other regulatory molecules that drive tumor growth." (PMID 38248333, 2024). "Patients with lower KPS scores had a higher predictive risk in the nomograms of this study, and the use of third-generation EGFR-TKIs for anti-tumor treatment should be conducted under the premise of improving the overall condition of patients as much as possible." (PMID 38515096, 2024). "Besides, we performed knockdown experiments to explore the role of epidermal growth factor receptor (EGFR) signaling pathway in MCs-tumor cell interactions, highlighting its potential as a prognostic marker." (PMID 39430754, 2024). "In contrast, blocking of EGFR signaling may decrease the expression of PD-L1, enhancing the cellular immune response against the tumor." (PMID 39343796, 2024). "EGFR-TKIs (EGFR Tyrosine Kinase Inhibitors) target the active site of the tyrosine kinase domain of EGFR, inhibiting its phosphorylation and activation and slowing down the progression of the tumor." (PMID 39273095, 2024). "We further analysed the correlation between CXCL12, CD44v6, HIF1A, TGFBR2 and KRT7 expression in metastatic tumor tissues & exosomes with sex, age, habit, Tumor Differentiation grade, TNM stage, EGFR mutation status, AE1, Chromogranin, CDX2, CEA, CK20, TTF-1 & CK7." (PMID 38877052, 2024). "Our laboratory and others have previously demonstrated a role for the chemokine interleukin-8 (IL-8, CXCL8) in mechanisms of tumor progression in several tumor types, including as a driver of resistance to chemotherapy, EGFR-targeted therapy, and immunotherapy." (PMID 39639338, 2024). "Furthermore, overexpression of GAS5 sensitizes resistant NSCLC cells to EGFR-TKIs and inhibits tumor growth in mice treated with gefitinib." (PMID 38200584, 2024). "Additionally, in OSCC, an increased expression of DNA methyltransferase 1 plays a role in promoting tumor growth by influencing ADAM9-mediated activation of the epidermal growth factor receptor (EGFR)-AKT signaling pathway." (PMID 38673838, 2024). "In particular, fetal tumor organoids were sensitive to the treatment of small molecule inhibitors targeting the EGFR/HER, such as afatinib, erlotinib, and sapitinib, while embryonal tumor organoids were sensitive to pan-FGFR inhibitors, such as erdafitinib, futibatinib, and ponatinib." (PMID 39567475, 2024).
tumor (continued). "Due to tumour heterogeneity, mixed responses and oligoprogression on the EGFR TKIs may occur when subclonal tumour cells harbouring different EGFR or other gene alterations co-exist with tumour cells still harbouring sensitive EGFR mutations." (PMID 38891886, 2024). "Our study demonstrates that tumor tolerance to TKIs could be a crucial mechanism contributing to incomplete responses during the early phase of EGFR-targeted therapy." (PMID 39041204, 2024). "The SUVmax of pulmonary lesions served as a predictive marker for EGFR mutations, whereas metabolic tumor volume and total lesion glycolysis were not related to EGFR mutation status." (PMID 39834943, 2024). "The transformation of tumor cells from an epithelial to a mesenchymal phenotype enhances the invasiveness and metastatic ability of the tumor and leads to resistance to certain treatment agents, including EGFR-TKIs." (PMID 39227379, 2024). "Therefore, targeting EMT represents a promising strategy to effectively kill tumor cells and overcome resistance to EGFR-TKIs in NSCLC." (PMID 39375945, 2024). "Thus, the variable region of cetuximab would be exposed to the solvent, providing the ability to selectively bind EGFR-overexpressing tumor cells to the VLPs." (PMID 38673914, 2024). "Previous studies have shown that both EGFR-TKIs and BA promote autophagy in many tumor types." (PMID 38764025, 2024). "In NSCLC, it has been reported that EGFR mutation status and tumor PD-L1 expression are associated with the efficacy of EGFR-TKIs, but there is not enough information regarding this association in pulmonary sarcomatoid carcinoma." (PMID 39207576, 2024). "In cases where clones of cells carrying activating KRAS mutations emerge in tumours that are resistant to anti‐EGFR therapies, it is notable that most of the cells in the tumour do not carry this mutation." (PMID 38887984, 2024). "Therefore, in tumor tissues, autophagy is impaired, and internalized EGFR accumulates within EGFRM NSCLC cells, reducing the susceptibility of EGFR to targeted therapy." (PMID 38338651, 2024). "Thus, only in the group of nonsmoking patients did we find an increased expression level of TP63 and EGFR genes in tumor tissue compared to peritumor tissue." (PMID 38540309, 2024). "Additionally, we demonstrated co-expression and colocalization of EGFR and the cell cycle genes in the tumor microenvironment by scRNA-seq and spatial transcriptomic analyses." (PMID 38772416, 2024). "For example, angiotensin II, a major signalling molecule of the renin-angiotensin system, can promote tumour growth by inducing angiogenesis and tumour cell proliferation through increased expression of vascular endothelial growth factor (VEGF) or epidermal growth factor receptor (EGFR)." (PMID 38487860, 2024). "Studies have shown that MET gene amplification can often coexist with other tumor driver genes in NSCLC, such as EGFR and KRAS mutations and ALK and ROS1 fusions, indicating that MET gene amplification may not act as an intrinsic driver factor within tumors." (PMID 39582541, 2024).
tumor (continued). "This may be a result of the known correlation between immune cold CIN tumours and EGFR amplification or a direct impact of EGFR signaling." (PMID 38744099, 2024). "However, the development of targeted therapies for EGFR-mutant ADC is hindered by tumor heterogeneity and complex TME interactions that influence tumor progression and treatment responses." (PMID 38546390, 2024). "TKIs, as targeted drugs, inhibit kinase activity and autophosphorylation by competitively binding to the ATP binding site of the EGFR tyrosine kinase domain, which blocks the signal transduction mediated by EGFR and thus inhibits the proliferation of tumor cells." (PMID 39777265, 2024). "Our data highlighted that upon drug treatment pulmonary tumor growth is decreased, and a defined tumor-enriched epithelial subpopulation is affected by shutting down EGFR signaling and cell growth, while the normal epithelial components are virtually unaffected." (PMID 38546390, 2024). "In metastatic colon cancer, deregulation of the RAS-MEK1/2-ERK1/2 signaling pathway downstream of epidermal growth factor receptor by RAS-associated mutations confers a selective growth and survival advantage to tumor cells giving them an acquired resistance to anti-EGFR therapy." (PMID 38247543, 2024). "Conjugating TNF-α with anti-EGFR antibodies, such as cetuximab, may be an effective immunocytokine therapy for tumours." (PMID 38789573, 2024). "Subsequently, we compared the expression of αvβ6 and EGFR in normal and tumor cells." (PMID 38633382, 2024). "The interaction between the migratory subtype and IL6high iCAF was the most specific and EGFR-related, which may indicate its importance in promoting tumor progression and mesenchymal transition for cancer progression." (PMID 38892065, 2024). "Additionally, EGFR inhibition sped up the release of cell-free DNA (cfDNA) from senescent tumor cells." (PMID 38279998, 2024). "Indeed, an EGFR × CD3 BiTE was able to induce the bystander effect by killing EGFR− tumor cells when co-cultured with EGFR+ cells." (PMID 38339258, 2024). "EGFR amplification likely contributed to aggressive tumor growth, while PIK3CA amplification, through activation of the PI3K/AKT pathway, may have facilitated immune evasion and treatment resistance." (PMID 39796090, 2024). "The tracer could visually differentiate EGFR-positive and -negative tumors in preclinical models, with high specificity for EGFR (a marked decrease in positive tumor uptake when imaging with [89Zr]Zr-control-IgG-SpyTag-∆N-SpyCatcher)." (PMID 39768978, 2024). "The prevalence of HER2 tumor mutations without EGFR mutations was then estimated to be ~2% (164/9206)." (PMID 39692700, 2024). "In EGFR-TKI-resistant NSCLC cells, SFN treatment reduces EGFR expression and inhibits tumor growth." (PMID 38255882, 2024). "Additionally, VEGF interacts with the epidermal growth factor receptor pathway to promote tumor cell proliferation and survival, highlighting its multifaceted influence on tumor biology." (PMID 38542288, 2024). "Acquisition of an aggressive phenotype, as evidenced by enhanced motility or ability to invade, may be explained by increased ADAM17-mediated EGFR transactivation in such tumours." (PMID 38397010, 2024). "EGFR-mutant-specific antibodies cannot replace conventional molecular methodologies, but they could be very helpful in small tumor samples with poor material." (PMID 38953007, 2024). "This phase I study in patients with astrocytoma grade 4 (AG4) examines whether infusions of EGFR BATs in combination with standard radiation and chemotherapy are safe and feasible and if the therapy induces systemic anti-tumor immunity." (PMID 38263486, 2024).